MMP2 (matrix metallopeptidase 2)
Diseases named in the same sentence as MMP2 in open-access papers (continued):
Sharing a sentence is not in itself a finding about the gene and the disease.
tumor (continued). "When the linker is cleaved by the matrix metalloproteinases MMP2, -9 or 14, important regulatory enzymes in the extracellular matrix of many tumour types, the CPP-Cy5 conjugate is “released”, and can enter the surrounding tumour cells." (PMID 27713270, 2010). "During this process, degradation of the extracellular matrix and components of the basement membrane by proteases, such as matrix metalloproteinase (MMP)-2, MMP-9, and urokinase plasminogen activator (uPA), plays a critical role in tumor invasion and metastasis." (PMID 20429953, 2010). "Stimulation of the invasive phenotype of tumour cells in 3D co-cultures with fibroblasts could be correlated with increased production of S100A4 and MMP-2." (PMID 20723242, 2010). "In particular, MMP-2 and MMP-9 were reported to correlate with tumour grade and metastasis." (PMID 20587068, 2010). "Since our previous studies demonstrated that CIB1-KO mice have decreased growth factor-mediated angiogenesis, and CIB1-KO ECs have attenuated MMP-2 expression, we hypothesized that CIB1-KO mice may also have a defect in tumor-induced angiogenesis." (PMID 20804551, 2010). "Due to the heterogeneous distribution of MMP2 in the tumour tissue immunohistochemical quantification was not possible." (PMID 19292920, 2009). "Among MMPs, MMP-2 (gelatinase A) and MMP-9 (gelatinase B), are present in large quantities in cancer tissues, and accumulating evidence indicates that MMP-2 and MMP-9 play critical role during tumor invasion and metastasis." (PMID 19624845, 2009). "Other paracrine factors such as TGF-β and MMP-2 are secreted but are not regulated by these bone-tumor interactions." (PMID 19192289, 2009). "VEGF, NF-κB, PCNA, MMP-2 and MMP-9 expression in tumor tissue was also assessed." (PMID 18983651, 2008). "Tumor tissues derived from curcumin treated mice showed that curcumin inhibibited proliferation (PCNA and Ki67 staining), induced apoptosis (TUNEL staining), metastasis (uPA, MMP-2 and MMP-9 staining), and angiogenesis (CD31 and VEGF staining)." (PMID 18226269, 2008). "There have been reports linking other extracellular proteases, such as MMP-9, MMP-1 and uPA with FAK signalling in other tumour cell types, but until now MMP-2 has not been reported to be involved." (PMID 18349846, 2008). "The effect on MMP-2 production does not seem to be endothelial-specific, since a decrease in MMP-2 secretion by HT1080 tumour cells was also observed after treatment with 15 μM DTD." (PMID 18782185, 2008). "Previous reports have shown a functional link between FAK-ERK1/2-JNK and MMP-2 expression in tumour and noncancerous cells." (PMID 18349846, 2008). "In this study, we demonstrated that MMP-2 and MMP-9 are produced predominantly by mesothelial cells and their expression is up-regulated once there is a contact between the mesothelial cells and the tumor cells." (PMID 19662219, 2007). "Their studies revealed further elevated MMP2, MMP3, and TIMP2 concentrations from patients after tumour resection, which might function as a predictive value for early detection of tumour recurrence." (PMID 16901349, 2006). "Lysophosphatidic acid (LPA), a phospholipid produced from malignant ovarian epithelium, can enhance the expression of CXCL8 by tumor cells and stimulate EOC cell invasion by enhancing membrane type-1 (MT1) matrix metalloproteinase (MMP) mediated activation of MMP2." (PMID 16824216, 2006). "However, MMP-2 null and MMP-9 null fibroblasts combined with FaDu tumor cells formed significantly larger tumors than FaDu cells injected alone (p = 0.04 and 0.009, respectively)." (PMID 16515711, 2006). "We have previously reported that all of the tumor lines of the model express similar levels of MT1-MMP but none express detectable MMP-2." (PMID 16608535, 2006). "Unlike the fibroblast invasion assay alone, FaDu tumor cells in coculture with MMP-2 null fibroblasts demonstrated 50% less invasion compared to FaDu cells in coculture with MMP-9 null or WT fibroblasts." (PMID 16515711, 2006).
tumor (continued). "Incubation of sub-confluent FaDu tumor cells atop type I collagen with serum-free conditioned media from WT, MMP-2 null, MMP-9 null or MT1-MMP null fibroblasts failed to induce FaDU tumor cell invasion (data not shown) over a 7 day incubation period." (PMID 16515711, 2006). "However, it is well known that, for example, the ratios of active to total MMP2 and MMP9, respectively are changed in tumour tissue and also in plasma." (PMID 16901349, 2006). "In all, 58% of the patients presenting with MMP-2-positive and oestrogen (n=59) or progesterone (n=96) receptor-negative primary tumour were alive after the 10 years of follow-up." (PMID 14520459, 2003). "The 10-year RFS of the patients with MMP-2-negative primary tumour was 57%, whereas it was 48% in those patients with a tumour displaying MMP-2 positivity (P=0.05), the overall survival being 64% vs 59%, respectively." (PMID 14520459, 2003). "It is interesting that 90% of the patients with an oestrogen receptor negative, MMP-2 negative or 95% of the patients with a progesterone receptor negative, MMP-2 negative primary tumour were alive after the 10 years of the follow-up." (PMID 14520459, 2003). "The 10-year RFS was 60% in patients with a low-grade (+) and 56% in those with a strongly positive (++) tumour, compared to 64% in patients with an MMP-2-negative tumour." (PMID 14520459, 2003). "Explicit differences between MMP-2 and MMP-9, with respect to both levels of active enzyme and correlations with clinicopathological parameters, strongly suggest different roles for the gelatinases in tumour progression." (PMID 12085179, 2002). "The mRNAs corresponding to EMMPRIN and MMP-2 were seen in neoplastic cells as well as inendothelial cells both inside and outside the tumor pseudo-capsule, whereas MT1-MMP was seen only within the tumors.The estimated mRNA levels of EMMPRIN and MMP-2 covariated significantly." (PMID 18521441, 2001). "A large number of MMP-9-positive macrophages correlated (P < 0.05) with poor tumour differentiation, whereas weak or absent epithelial MMP-2 staining reached near significance (P < 0.08)." (PMID 9310250, 1997). "Moreover, MMP-2, a collagenase IV is involved in tissue remodeling and tumor invasion by degrading extracellular matrix components, MMP-9 is involved in developing malignancies and enhances tumor angiogenesis, progression, invasion, and metastasis." (PMID 40740599, 2025). "Further Western blot analysis showed that RRM2 regulated the expression levels of MMP2, MMP9 and EMT-related proteins (N-Cadherin, Vimentin, Snail), suggesting that RRM2 may promote tumor cell invasion and metastasis by promoting matrix degradation and inducing epithelial mesenchymal transition." (PMID 41333212, 2025). "Furthermore, cells in the myCAF-(F-POSTN) and iCAF-(F-ALPL) groups expressed high levels of matrix metalloproteinases (MMPs; e.g., MMP2, MMP14, MMP23B, and MMP19), indicating that these cells are involved in degradation of the basement membrane and ECM to facilitate tumor metastasis." (PMID 40319103, 2025). "Lastly, Lewis mouse transplant tumor experiments showed that SH inhibited tumor growth, reduced the protein expression of Ki-67, VEGFA and CD31 in transplanted tumor tissues, and the mRNA expression of MMP-2 and Bcl-2, while promoting the expression of Bax mRNA." (PMID 41444284, 2025). "MMP2 expression appeared in a microfocal pattern and did not correlate with tumor growth patterns." (PMID 41211185, 2025). "Previous studies have shown that this alkaloid can (i) inhibit tumor cell proliferation while at the same time inducing apoptosis; (ii) affect signaling pathways (e.g., MAPK/ERK and PI3K/Akt); and (iii) inhibit tumor cell migration and invasion (e.g., MMP-2 and MMP-9)." (PMID 40710294, 2025).
tumor (continued). "In addition, the expression of metastasis-related markers matrix metallopeptidase 2 (MMP2), MMP9, and intercellular cell adhesion molecule-1 (ICAM1) was decreased, suggesting that METTL3 overexpression suppressed transcription of key tumor metastasis genes." (PMID 41208889, 2025). "Indeed, DNJ has been shown to inhibit the expression of MMP2 and MMP9, upregulate TIMP-2, and alter cell surface glycan-binding motifs, which are crucial in extracellular matrix remodeling, differentiation, and migration of tumor-derived cells." (PMID 40428492, 2025). "Therefore, we hypothesized that MMP-2 inhibition could recruit TILs into COAD by suppressing TGF-β activation and reducing ECM remodeling to inhibit tumor progression." (PMID 40611940, 2025). "By attenuating upstream mediators such as TNFα and VEGFα, and downstream effectors like COX-2 and MMP-2, HA extract and L-NAME co-treatment effectively disrupt multiple nodes of the oncogenic network, potentially limiting both the expansion and the invasive capacity of tumor cells." (PMID 40179064, 2025). "Therefore, to provide deeper insight into the effects of TA on tumor growth, angiogenesis and immunomodulation, we evaluated blood biomarkers, macrophage polarization and their interconnections with VEGF, MMP-2/-9, COX-2, microvessel density, and cytokine levels." (PMID 41009634, 2025). "MMP-2 expression correlated with the tumor grade in BCC and AK but not in cSCC." (PMID 38248804, 2024). "Furthermore, MMP-2 plays a pivotal role in the degradation of the extracellular matrix (ECM) during cancer progression, inducing cancer cells to migrate beyond the primary tumor to create metastatic foci." (PMID 39682720, 2024). "MMP-2 (gelatinase A) is an endopeptidase that degrades previously cleaved ECM components (by collagenases), such as collagen IV from the basement membrane, as well as other non-fibrillar collagens (V, VII, X); gelatin; fibronectin; and type I, II and III collagen, enabling tumor cell progression." (PMID 39063046, 2024). "For now, it is well established that VEGF, FGF-2, and ANG-2 upregulate MT1-MMP, MMP-2, and MMP-9 expression: consistently, a positive correlation has been observed between the levels of these angiogenic factors and those of MT1-MMP, MMP-2 or MMP-9 in tumor tissues." (PMID 39120324, 2024). "Considering the whole process of angiogenesis in the RCC samples studied, the pathway associated with the actions of MMPs may be due to hsa-miR-15b-5p, hsa-miR-99b-5p, hsa-miR-181a-5p as they exert their role in their interactions as tumor suppressors with MMPs, especially with MMP-9 and MMP-2." (PMID 39062015, 2024). "We found through gelatine zymography assays that CM derived from the co-culture experiments (MLKL-overexpressing tumour cells and macrophages) had an improved ability to digest gelatine, but this property was reversed by MMP inhibitors, MET inhibitors and GW, primarily affecting by MMP2 and MMP9." (PMID 39025845, 2024). "However, Age, sex distribution, tumor size, and histological type of cancer do not significantly differ between low and high MMP2 expression groups." (PMID 38978899, 2024). "Furthermore, the upregulation of MMP-2, MMP-3, and myeloperoxidase highlights the role of these tumors in host-immune interactions, while the decrease in osteopontin and proliferin suggests a shift toward a less favorable tumor microenvironment." (PMID 38890285, 2024). "Meanwhile, the increase in MMP-2 MMP-9, SNAI1 and TWIST1 protein levels in the IL-22 group suggests that IL-22 may regulate MMP expression by activating the PI3K/AKT signaling pathway, enhancing tumor cell invasion and metastasis." (PMID 39073546, 2024).
tumor (continued). "Research indicates that Apelin can enhance the expression of MMP‐2 through the activation of the PI3K/Akt pathway and FOXO3A, leading to the degradation of the ECM and promoting the motility and migration of vascular smooth muscle cells (VSMCs), which facilitates tumour invasion and metastasis." (PMID 39434201, 2024). "The reliance on IHC for assessing MMP2 expression, while useful, may not fully capture the dynamic and multifaceted role of MMP2 in tumor biology." (PMID 38978899, 2024). "Consequently, MMP-2 expression levels serve as a prognostic indicator for patient survival, irrespective of tumor size and ulceration." (PMID 39769318, 2024). "In addition, other metastasis related genes (VEGFA, MMP-2 and MMP-9) decreased in tumor cells." (PMID 37853415, 2023). "Aberrant expression of VM production-related proteins (MMP2, MMP9, VEGFA, Laminin, Wnt3a, RHOA) as well as immune checkpoint (PD-L1) in tumors and the occurrence of EMT process are considered to be important drivers of VM formation and tumor development as well as metastasis." (PMID 37407689, 2023). "Our results confirm that MMP-2 is indeed a target protein of CTX, based on which CTX analogs might be optimized by phage display technology for higher affinity and specificity to further improve specific targeting of tumor cells." (PMID 37394009, 2023). "During tumor development, MMP2 and MMP9 may be involved in the regulation of tumor angiogenesis by undermining immunity, activating the TGF-β signaling, and releasing VEGF and bFGF, thus promoting the rapid growth and distant metastasis of tumor cells." (PMID 37144126, 2023). "Therefore, CEMIP may have a positive correlation with MMP2, MMP7, MMP13, and MMP14 and regulate tumor cell EMT through MMPs to promote tumor cell migration." (PMID 37662915, 2023). "A previous report indicated that SS could repress MMP-9 expression in tumor cells without affecting MMP-2 expression." (PMID 38098039, 2023). "Patients with uveal melanoma positive for MMP-2 and MMP-9 had a significantly higher incidence of metastatic disease and lower survival rate, indicating that proteolytic enzymes, such as MMPs, may play a central role in tumor spread." (PMID 36902129, 2023). "The pharmacokinetics and efficacy studies also indicated higher tumor accumulation and extended survival rates in C26 tumor-bearing mice treated with the MMP-2 cleavable CLs as compared to the non-cleavable CLs with no remarkable sign of toxicity in healthy tissues." (PMID 36910721, 2023). "In addition, the vaccine regulated MMP‐2 activity and degraded various collagen components of tumor ECMs, which broke the ECM barrier, alleviated the immunosuppressive environment, and enhanced CD8+ T cells tumor invasion and killing." (PMID 37439462, 2023). "TAM-induced MMP-2 and MMP-9 could promote angiogenesis and tumor vascularization." (PMID 37441589, 2023). "Stromal fibroblasts release inactive MMP-2 (pro-MMP-2) that is activated by cancer-cell-derived MT1-MMP, resulting in significantly enhanced invadopodia formation and matrix degradation, even in tumor cell lines that, independently, are incapable of invadopodial matrix degradation." (PMID 37046830, 2023). "Moreover, MMP2 and MMP9 can be affected by many tumor-related signaling pathways or cytokines." (PMID 37686118, 2023). "Mechanistically, XRCC1 inhibits tumour cell invasion and metastasis by regulating the expression of tissue inhibitors of matrix metalloproteinase-2 (TIMP-2) and TIMP-1, leading to the suppression of the expression of metastasis-related markers matrix metalloproteinase-2 (MMP-2) and MMP-9." (PMID 37679817, 2023). "Based on it, a ß-Cyclodextrin (β-CD) modified matrix metalloproteinase-2 (MMP-2) responsive liposome (LRC-GEM-PFD) was constructed by a thin-film hydration method to regulate PSCs, and RGD peptides were also modified onto the liposomes for targeting tumor cells." (PMID 36762192, 2023).
tumor (continued). "In vivo experiment showed that depletion of CD4(+) T lymphocytes lead to inhibition of antitumor activity and decreased antibodies against MMP-2, indicating that contribution of immune response against MMP-2 might be potential novel tumor methods for cancer therapy." (PMID 37766868, 2023). "Furthermore, MMP-2, also called gelatinase A, also plays a significant role in ECM degradation because it can degrade collagen type IV during cancer progression, allowing cancer cells to migrate from the primary tumor to form metastasis." (PMID 36903626, 2023). "Interestingly, MMP-2 and MMP-9 can bind to low-density lipoprotein receptor-related protein 1 (LRP1), activate ERK, inhibit the JNK pathway, facilitate tight adhesion of tumor cells to the stroma, and induce tumor cell invasion into blood vessels and lymphatic vessels." (PMID 37359527, 2023). "Since MMP-2 was enriched in TME, MMP-2 linker could be cleaved within the tumor microenvironment, and the free D-type anti-PD-L1 peptide can bind to the PD-L1 receptor on tumor cells to block the potential impact of tumor cell immune escape." (PMID 35547769, 2022). "Moreover, we also found that MTAP may downregulate the expression of MMP2 and VEGFD in BC cells by inhibiting ODC activity, leading to the suppression of tumor angiogenesis." (PMID 35541910, 2022). "SLPI may also promote vascular invasion via induction of MMP-2 and MMP-9 production by tumor cells." (PMID 35842496, 2022). "Moreover, the expression of MMP2 and MMP9 was reversed when FN1 expression was knocked down in HOXD11-overexpressing cells, which suggested the indispensable role of FN1 in HOXD11-mediated tumor progression." (PMID 36151071, 2022). "Therefore, this study is the first to target MRTK, a rare tumour, in combination with the MMP inhibitor doxycycline, aiming to determine whether EMT, as well as the differential expression of MMP2 and MMP9, exists in MRTK." (PMID 36408277, 2022). "In this study, the results showed that CCL25/CCR9 could increase the expression of MMP2 and MMP9 by activating PI3K/AKT in SACC, which was confirmed in xenograft tumor mice, suggesting that CCL25/CCR9-activated PI3K/AKT might modulate MMPs through the transcription factor SLUG." (PMID 36003306, 2022). "In addition, patients in S3 had high levels of the macrophage marker gene CD68 and EMT marker genes such as MMP2 and MMP9, indicating that these cells in the tumor microenvironment may play important roles in tumor progression." (PMID 35124891, 2022). "The M2 type of macrophages releases matrix metalloproteinases MMP2 and MMP9 to degrade the extracellular matrix, which further stimulates the migration of vascular endothelium and induces angiogenesis and promotes the proliferation and metastasis of tumor cells." (PMID 35847897, 2022). "Interestingly, both MMP-2 and MMP-9 were reported to be overexpressed in equine sarcoid, suggesting that tumor progression could be the result of a mechanism responsible for proliferation and more collagen production." (PMID 36518899, 2022). "On the other hand, MMP-9/MMP-2 protein expression may be downregulated by inhibiting the activation of Smad2/3 (pSmad2/3), thereby inhibiting the occurrence of EMT and weakening the metastatic ability of tumor cells." (PMID 35936728, 2022). "In addition, Astragaloside IV and Curcumin down-regulated the expression of fibroblast growth factor 2, matrix metalloproteinase 2 (MMP2), vascular endothelial growth factor (VEGF), hepatocyte growth factor, and synergistically inhibited nude-mouse model of HCC tumor growth and angiogenesis." (PMID 35907976, 2022). "Therefore, it was speculated that JM2 could inhibit the expression of MMP2 and MMP9 and consequently inhibited the migration and invasion of tumor cells." (PMID 35332127, 2022). "Therefore, we speculate that the high expression levels of MMP2 and MMP9 promote EMT in MRTK, thus promoting tumour migration and invasion and leading to malignant tumour progression." (PMID 36408277, 2022).